FAM107A (family with sequence similarity 107 member A)
Description:
Stress-inducible actin-binding protein that plays a role in synaptic and cognitive functions by modulating actin filamentous (F-actin) dynamics. Mediates polymerization of globular actin to F-actin. Also binds to, stabilizes and bundles F-actin. Involved in synaptic function by regulating neurite outgrowth in an actin-dependent manner and for the acquisition of hippocampus-dependent cognitive function, such as learning and long-term memory (By similarity). Plays a role in the actin and microtubule cytoskeleton organization; negatively regulates focal adhesion (FA) assembly promoting malignant glial cell migration in an actin-, microtubule- and MAP1A-dependent manner. Also involved in neuroblastoma G1/S phase cell cycle progression and cell proliferation inhibition by stimulating ubiquitination of NF-kappa-B subunit RELA and NF-kappa-B degradation in a COMMD1- and actin-dependent manner. May play a role in tumor development.
Synonyms: DRR1; TU3A
Tractability: Antibody: its Gene Ontology location is reachable by antibodies, with medium confidence. PROTAC: ubiquitination databases record sites on it.
Gene: Protein-coding gene on chromosome 3 (58,564,117 to 58,627,651, reverse strand). Ensembl gene ENSG00000168309.
Subcellular location: Nucleus; Cytoplasm, cytoskeleton, stress fiber; Cell junction, focal adhesion; Cell projection, ruffle membrane; Synapse
Subcellular location (Human Protein Atlas): Nuclear speckles
Gene Ontology:
Molecular function: protein binding
Biological process: negative regulation of focal adhesion assembly; negative regulation of G1/S transition of mitotic cell cycle; positive regulation of cell migration; positive regulation of protein ubiquitination; regulation of actin cytoskeleton organization; regulation of cell growth; regulation of microtubule cytoskeleton organization; regulation of protein stability; actin filament bundle assembly; actin filament polymerization; cellular response to glucocorticoid stimulus; cellular response to nutrient levels; cognition; negative regulation of long-term synaptic potentiation; regulation of postsynapse assembly
Cellular component: actin cytoskeleton; cytoplasm; focal adhesion; nuclear speck; nucleus; ruffle membrane; stress fiber; neuron projection; synapse; glutamatergic synapse; postsynaptic actin cytoskeleton; presynaptic actin cytoskeleton
Genetic constraint (gnomAD): Loss-of-function variants: 18 observed, 14.15 expected, observed/expected ratio (o/e) 1.27, 90% interval 0.88 to 1.81. The upper end of that interval is the gene's LOEUF score, 1.81, which puts it in group 6 of 6, group 1 being the genes least tolerant of losing a copy. Missense variants: 203 observed, 192.49 expected, observed/expected ratio (o/e) 1.05, 90% interval 0.94 to 1.18. Synonymous variants: 82 observed, 79.17 expected, observed/expected ratio (o/e) 1.04, 90% interval 0.87 to 1.25.
Homologues: Orthologues: chimpanzee FAM107A (100% identical), macaque FAM107A (99% identical), guinea pig FAM107A (99% identical), dog FAM107A (97% identical), rabbit FAM107A (95% identical), rat Fam107a (92% identical), mouse Fam107a (91% identical), tropical clawed frog fam107a (71% identical), zebrafish FAM107A (58% identical), zebrafish FAM107A (47% identical), Drosophila melanogaster CG9328 (28% identical). Paralogues in human: FAM107B (51% identical).
Diseases named in the same sentence as FAM107A in open-access papers:
FAM107A is named in the same sentence as 54 diseases in open-access papers, as found by Europe PMC text mining. Sharing a sentence is not in itself a finding about the gene and the disease. The quoted sentences say what the papers report.
renal cell carcinoma (10 papers, 2010 to 2023). "FAM107A (actin-associated protein), also known as DRR1 (downregulated in renal cell carcinoma) and TU3A (Tohoku University cDNA clone A on chromosome 3), is located in the 3p region." (PMID 36010909, 2022). "FAM107A, originally identified in a commonly deleted region on 3p21 in renal cell carcinoma, appears to function as a tumour suppressor." (PMID 29755658, 2018). "FAM107A was described in renal cell carcinoma as a putative tumor-suppressor gene according to its role in the regulation of apoptotic processes." (PMID 25945129, 2015). "An early study also revealed the downregulation of FAM107A in renal cell carcinoma." (PMID 38188687, 2023). "We noticed that several stress response genes such as Drr1 (down-regulated in renal cell carcinoma 1, also called family with sequence similarity 107 (Fam107A)), Edn1, Klf9, and Nfkbia39, 40, 41, 42 were significantly increased in Cpeb4GT/GT spinal cord, which was independently validated by RT-qPCR." (PMID 27381259, 2016). "Fam107a encodes a ubiquitously expressed protein that was first described in the context of renal cell carcinoma, in which Fam107a expression is reduced or absent due to promotor hypermethylation." (PMID 20525385, 2010).
lung carcinoma (6 papers, 2016 to 2022). "On the contrary, in the group of 60 lung cancer patients with decreased FAM107A expression, DNA methylation was observed in minor amount of samples and thus was excluded by the authors as the mechanism of its inactivation." (PMID 28710449, 2017). "The expression level of FAM107A is decreased in patients with NSCLC, whereas the high levels of expression of HS6ST2 are observed in lung cancer cell lines." (PMID 30453959, 2018). "It has been evidenced that FAM107A is frequently lost in various types of cancer, including ovarian cancer, cell carcinoma (RCC), prostate cancer and lung cancer cell lines." (PMID 28830341, 2017). "Of 30 top ranked genes, FAM107A, MAMDC2, SOX17, TCF21, PTPRH, and CDO1 have been previously reported with aberrant DNA methylation in lung cancer." (PMID 27610367, 2016).
bipolar disorder (5 papers, 2014 to 2026). A disorder of the brain that causes unusual shifts in mood, energy, activity levels and the ability to carry out day-to-day tasks. "A number of studies suggested that human chromosome 3p14, the location of FAM107A, is linked to psychiatric disorders, such as schizophrenia, bipolar disorder and Asperger syndrome." (PMID 24748967, 2014). "In multiple studies, it has been discovered that Fam107a has differential expression in psychiatric disorders such as schizophrenia, bipolar disorder, and Alzheimer’s disease, suggesting its involvement in the pathophysiology of these disorders." (PMID 41552777, 2026). "FAM107A mRNA expression was increased in postmortem RNA samples from the dorsolateral prefrontal cortex (Brodman area 46) of patients suffering from schizophrenia and bipolar disorder." (PMID 24748967, 2014). "Interestingly, Fam107a and Agxt2l1 are deregulated in prefrontal cortex of patients with schizophrenia and bipolar disorder." (PMID 25472829, 2014). "Moreover, dysregulated FAM107A expression has been reported in postmortem PFC samples of suicide victims with schizophrenia and bipolar disorder." (PMID 31032362, 2019).
neuroblastoma (5 papers, 2016 to 2023). Neuroblastoma (NB) is the most common solid, extracranial childhood tumor. "Actin-associated protein FAM107A, also known as DRR1 has been shown to link COMMD1 to nuclear F-actin in neuroblastoma cells." (PMID 34943955, 2021). "FAM107A is involved in multiple cellular processes, such as the negative regulation of the G1/S phase transition of the mitotic cell cycle, and has been linked to various human diseases, including neuroblastoma." (PMID 37446311, 2023). "In neuroblastoma, FAM107A forms a complex with F-actin to negatively regulate cell cycle progression through suppressing cyclin D1 expression." (PMID 38188687, 2023).
glioblastoma (3 papers, 2022 to 2024). The most malignant astrocytic tumor (WHO grade IV). "Arnold and colleagues designed a chimeric DNA-FANA ASO directed against downregulated in renal carcinoma (DRR)/FAM107A, which is a gene that is highly expressed in invasive glioblastoma stem cells (GSCs) and promotes GSC invasion." (PMID 38792022, 2024). "In glioblastoma, FAM107A was downregulated during tumorigenesis and upregulated in the process of tumor invasion, which promotes cell invasion and epithelial-mesenchymal transformation through the activation of AKT." (PMID 35669436, 2022). "However, another study showed that FAM107A could promote glioblastoma progression and enhance the migration capacity of glioblastoma cells." (PMID 36010909, 2022).
prostate carcinoma (3 papers, 2017 to 2022). A carcinoma that arises from epithelial cells of the prostate gland. "The GEPIA database revealed that FAM107A expression was reduced in PCa tissues, and survival analysis revealed that high levels of FAM107A expression were associated with a favorable OS rate in patients with prostate cancer." (PMID 36010909, 2022). "In conclusion, these results suggest that hypermethylation of the FAM107A promoter region inhibited its expression in prostate cancer cells and that DNMT1 was involved in maintaining hypermethylation." (PMID 36010909, 2022). "We revealed that restoring FAM107A expression in prostate cancer cell lines such as DU 145 and PC 3 inhibited cell cycle progression, increased the proportion of cells in G1, and inhibited the expression of cyclin D1, a key protein in the G1 phase." (PMID 36010909, 2022). "In this study, the expression of FAM107A in DU 145 and PC 3 cell lines was restored to some extent by treating prostate cancer cells with the demethylating drug 5-Aza or by knocking down the expression of DNMT1 in siDNMT1 cells." (PMID 36010909, 2022). "The results show that FAM107A could regulate prostate cancer progression through the focal adhesion kinase (FAK) pathway." (PMID 36010909, 2022). "However, what exactly is the specific mechanism of FAM107A activity in prostate cancer?" (PMID 36010909, 2022).
renal carcinoma (3 papers, 2006 to 2022). A carcinoma arising from the epithelium of the renal parenchyma or the renal pelvis. "In summary, downregulated FAM107A facilitates the proliferation, migration, and invasion in bladder cancer and renal cancer cells." (PMID 35669436, 2022). "The analyses demonstrated a relatively lower expression of FAM107A in bladder cancer and renal cancer cell lines." (PMID 35669436, 2022). "To further investigate the effect of FAM107A on bladder cancer, we firstly examined the expression of FAM107A in multiple bladder cancer cell lines and renal cancer cell lines." (PMID 35669436, 2022). "An experiment in vitro showed FAM107A knockdown promoted the proliferation, migration, and invasion of bladder cancer and renal cancer cells." (PMID 35669436, 2022). "Importantly, FAM107A was recognized as a novel potential tumor-suppressor gene in bladder cancer and renal cancer by inhibiting the progression of cancer." (PMID 35669436, 2022). "That said, FAM107A may be served as an anti-cancer gene in bladder cancer and renal cancer." (PMID 35669436, 2022). "Likewise, a lower expression of FAM107A was also noted in renal cancer cell lines." (PMID 35669436, 2022).
gastric cancer (2 papers, 2021 to 2022). A primary or metastatic malignant neoplasm involving the stomach. "Compared with normal tissues, ADAM12, CEP55, LRFN4, and INHBA were up-regulated in gastric cancer samples, while ADH1B, DPT, FAM107A, and LOC100506388 were downregulated." (PMID 34686626, 2021).
Hodgkins lymphoma (2 papers, 2018 to 2022). A heterogeneous group of malignant lymphoid neoplasms of B-cell origin characterized histologically by the presence of Hodgkin and Reed-Sternberg (HRS) cells in the vast majority of cases. "Besides, a combined linkage and association analysis of classical Hodgkin lymphoma showed low or absent FAM107A expression in Hodgkin Reed-Sternberg cell lines and in Hodgkin Reed-Sternberg cells in Hodgkin lymphoma tissue." (PMID 35669436, 2022). "Expression of FAM107A and SLC26A6 was low or absent in HRS cell lines and in HRS cells in Hodgkin lymphoma." (PMID 29755658, 2018). "Expression of FAM107A and SLC26A6 was low or absent in Hodgkin Reed-Sternberg (HRS) cell lines and in HRS cells in Hodgkin lymphoma tissue." (PMID 29755658, 2018).
laryngeal carcinoma (2 papers, 2017 to 2020). Carcinoma that arises from the laryngeal epithelium. "By RT-PCR we have confirmed complete FAM107A downregulation in laryngeal cancer cell lines (15/15) and primary tumors (21/21) and this finding was further supported by FAM107A protein immunohistochemistry (15/15)." (PMID 28710449, 2017). "A recent study showed that hypermethylation may lead to the low expression of FAM107A in laryngeal cancer, which is consistent with our results." (PMID 33376725, 2020). "The results, confirmed the complete lack of FAM107A expression in laryngeal cancer cell lines (15/15; 100%) and primary tumors (21/21; 100%)." (PMID 28710449, 2017).
laryngeal squamous cell carcinoma (2 papers, 2017 to 2021). A squamous cell carcinoma that arises from the larynx. "In summary, our study indicates, that in the course of laryngeal squamous cell carcinoma, FAM107A is inactivated by combined deletions and DNA methylation events." (PMID 28710449, 2017).
non-small cell lung carcinoma (2 papers, 2016 to 2022). A group of at least three distinct histological types of lung cancer, including non-small cell squamous cell carcinoma, adenocarcinoma, and large cell carcinoma. "Studies have shown that FAM107A is dramatically decreased non-small cell lung cancers (NSCLC) with a minority of samples showing promoter methylation." (PMID 27280700, 2016). "previous reports could show that FAM107A/DRR1 expression is significantly decreased in LUAD and non-small cell lung cancer (NSCLC) patients." (PMID 36067196, 2022).
Anxiety (1 paper, 2026). Intense feelings of nervousness, tension, or panic often arise in response to interpersonal stresses. "Remarkably, when we increased the expression of FAM107a in the hippocampus of the MR-deficient male mice, it was sufficient to partially rescue their increased anxiety phenotype." (PMID 41552777, 2026). "Overexpression of Fam107a in the hippocampus was sufficient to rescue the increased anxiety phenotype of glutamatergic MR knockout mice." (PMID 41552777, 2026). "Increase of Fam107a expression either in all CA3 neurons or specifically in glutamatergic CA3 neurons was sufficient to partially rescue the increased anxiety phenotype of glutamatergic MR KO mice." (PMID 41552777, 2026). "In the OF test, we found a significant interaction effect between genotype and overexpression of Fam107a on anxiety-like behavior." (PMID 41552777, 2026). "Interestingly, we observed that Fam107a overexpression in glutamatergic neurons was sufficient to reduce anxiety-like behavior in the OF." (PMID 41552777, 2026). "Here, we demonstrated that Fam107a is associated with the anxiety-like phenotype in mice lacking MR in glutamatergic neurons." (PMID 41552777, 2026). "Furthermore, with Fam107a we identify a previously unrecognized MR target gene, which as a stress-regulated actin-bundling factor can mediate the MR-dependent effects on anxiety-related behavior." (PMID 41552777, 2026).
bladder cancer (1 paper, 2022). "Our study indicates that FAM107A may be a putative tumor suppressor in bladder cancer and other tumors." (PMID 35669436, 2022). "Finally, the expression and potential biological functions of FAM107A were analyzed and verified in vitro experiments with bladder cancer cell lines." (PMID 35669436, 2022). "Since FAM107A was closely related to multiple cancers and acted as an important potential effector, a pan-cancer analysis of FAM107A was performed and the effect of FAM107A in bladder cancer cells was explored for the first time in this study." (PMID 35669436, 2022).
Cerebral ischemia (1 paper, 2025). Restriction of arterial blood supply to the brain associated with insufficient oxygenation to support the metabolic requirements of the tissue. "NAP-induced down-regulation of various ER stress genes in males, including those encoding the pro-neuroinflammatory Nkd2, Hsph1 (Hsp110/105) and Fam107a (DRR1), which were shown to exacerbate cerebral ischemia, and Mertk, the mediator of alpha-synuclein fibril uptake." (PMID 39715923, 2025).
cholangiocarcinoma (1 paper, 2022). A carcinoma that arises from the intrahepatic biliary tree (intrahepatic cholangiocarcinoma) or from the junction, or adjacent to the junction, of the right and left hepatic ducts (hilar cholangiocarcinoma). "Besides, low FAM107A expression linked to poor prognosis as for disease-free survival (DFS) was discovered in CHOL (Cholangiocarcinoma) (HR=0.38, Logrank p=0.038), HNSC (HR=0.67, Logrank p=0.019), OV (HR=0.78, Logrank p=0.044), PAAD (HR=0.6, Logrank p=0.024), PRAD (HR=0.52, Logrank p=0.0025)." (PMID 35669436, 2022).
glioma (1 paper, 2014). A benign or malignant brain and spinal cord tumor that arises from glial cells (astrocytes, oligodendrocytes, ependymal cells). "It is hypothesized that FAM107A acts as an actin-microtubule cross-linker to organize the cytoskeletons essential for FAs modulation and glioma invasion." (PMID 24748967, 2014). "Studies on glioma cells may help elucidate the functions of FAM107A in neural cells." (PMID 24748967, 2014). "However, FAM107A was also found to be highly expressed in the invasive component of gliomas and may drive tumor invasion by modulating the cytoskeleton." (PMID 24748967, 2014).
laryngeal tumors (1 paper, 2017). "This enabled us to indicate the FAM107A gene as a promising tumor suppressor gene candidate involved in larynx cancer development and to identify the main mechanisms of its inactivation in this type of cancer." (PMID 28710449, 2017). "However, we are the first who show that FAM107A is also downregulated in laryngeal tumors." (PMID 28710449, 2017). "In our study we confirmed the nuclear and cytoplasmic expression of this protein in non-tumor control mucosa and importantly showed the lack of FAM107A expression in laryngeal tumor samples." (PMID 28710449, 2017).
lung adenocarcinoma (1 paper, 2022). A carcinoma that arises from the lung and is characterized by the presence of malignant glandular epithelial cells. "The results showed lower protein expression of FAM107A in lung adenocarcinoma and UCEC than in normal tissues (P<0.05)." (PMID 35669436, 2022). "In addition, the expression of the FAM107A protein was also observed to be downregulated in lung adenocarcinoma and UCEC." (PMID 35669436, 2022).
lymphoma (1 paper, 2022). A malignant (clonal) proliferation of B- lymphocytes or T- lymphocytes which involves the lymph nodes, bone marrow and/or extranodal sites. "However, an upregulation of FAM107A was discovered in THYM and lymphoma." (PMID 35669436, 2022).
ovarian serous cystadenocarcinoma (1 paper, 2022). A malignant serous cystic epithelial neoplasm arising from the ovary. "The down-regulating expression of FAM107A between the normal tissues and tumor tissues was also detected in OV (Ovarian serous cystadenocarcinoma) and THYM(Thymoma) after including the normal tissues of the GTEx dataset as controls (P < 0.01)." (PMID 35669436, 2022).
prostate adenocarcinoma (1 paper, 2022). "To demonstrate how FAM107A regulates the progression of PCa, we first performed an enrichment analysis of the KEGG pathway using the CBioPortal database (Prostate Adenocarcinoma-Firehose Legacy)." (PMID 36010909, 2022).
Skin Cutaneous Melanoma (1 paper, 2022). "Using the “Pathological Stage Plot” module of GEPIA2, a correlation between FAM107A expression and the pathological stages of cancers was also detected, including KICH, KIRC, LIHC (Liver hepatocellular carcinoma), LUSC, SKCM (Skin Cutaneous Melanoma), STAD (all P<0.05)." (PMID 35669436, 2022).
testicular germ cell tumor (1 paper, 2022). A germ cell tumor arising from the testis. "However, there was an up-regulating expression of FAM107A in TGCT (Testicular Germ Cell Tumors) and UCS (Uterine Carcinosarcoma) (P < 0.01)." (PMID 35669436, 2022).